PDIA6 (protein disulfide isomerase family A member 6)
Description:
May function as a chaperone that inhibits aggregation of misfolded proteins. Negatively regulates the unfolded protein response (UPR) through binding to UPR sensors such as ERN1, which in turn inactivates ERN1 signaling. May also regulate the UPR via the EIF2AK3 UPR sensor. Plays a role in platelet aggregation and activation by agonists such as convulxin, collagen and thrombin.
Synonyms: ERp5; P5; TXNDC7
Tractability: Antibody: UniProt places it where antibodies can reach, with high confidence; UniProt predicts a signal peptide or a membrane-spanning region; its Gene Ontology location is reachable by antibodies, with medium confidence. PROTAC: ubiquitination databases record sites on it; its protein half-life has been measured; a small molecule that binds it is known.
Target class: Enzyme
Gene: Protein-coding gene on chromosome 2 (10,783,378 to 10,837,977, reverse strand). Ensembl gene ENSG00000143870.
Subcellular location: Endoplasmic reticulum lumen; Cell membrane; Melanosome
Subcellular location (Human Protein Atlas): Endoplasmic reticulum; Basal body; Centriolar satellite; Primary cilium
Pathways (Reactome):
Metabolism of proteins: Post-translational protein phosphorylation; Regulation of Insulin-like Growth Factor (IGF) transport and uptake by Insulin-like Growth Factor Binding Proteins (IGFBPs)
Cellular responses to stimuli: XBP1(S) activates chaperone genes
Gene Ontology:
Molecular function: protein binding; protein disulfide isomerase activity; protein-disulfide reductase activity
Biological process: protein folding
Cellular component: endoplasmic reticulum; endoplasmic reticulum lumen; endoplasmic reticulum-Golgi intermediate compartment; extracellular exosome; extracellular region; melanosome; plasma membrane; endoplasmic reticulum chaperone complex; endoplasmic reticulum membrane
Genetic constraint (gnomAD): Loss-of-function variants: 15 observed, 37.31 expected, observed/expected ratio (o/e) 0.4, 90% interval 0.27 to 0.62. The upper end of that interval is the gene's LOEUF score, 0.62, which puts it in group 2 of 6, group 1 being the genes least tolerant of losing a copy. Missense variants: 387 observed, 446.52 expected, observed/expected ratio (o/e) 0.87, 90% interval 0.8 to 0.94. Synonymous variants: 154 observed, 160.56 expected, observed/expected ratio (o/e) 0.96, 90% interval 0.84 to 1.1.
Homologues: Orthologues: chimpanzee PDIA6 (98% identical), macaque PDIA6 (98% identical), mouse Pdia6 (95% identical), dog PDIA6 (95% identical), rat Pdia6 (94% identical), rabbit PDIA6 (92% identical), pig PDIA6 (92% identical), guinea pig PDIA6 (91% identical), tropical clawed frog pdia6 (81% identical), zebrafish pdia6 (76% identical), Drosophila melanogaster CaBP1 (58% identical), Caenorhabditis elegans pdi-6 (55% identical). Paralogues in human: P4HB (25% identical), PDIA4 (23% identical), PDIA2 (22% identical), PDIA3 (22% identical), TXNDC5 (18% identical), PDIA5 (17% identical), PDILT (17% identical), TXNDC11 (16% identical), TMX3 (14% identical), ERP44 (13% identical), TMX1 (11% identical), TMX4 (10% identical), and 1 more.
Diseases named in the same sentence as PDIA6 in open-access papers:
PDIA6 is named in the same sentence as 54 diseases in open-access papers, as found by Europe PMC text mining. Sharing a sentence is not in itself a finding about the gene and the disease. The quoted sentences say what the papers report.
breast carcinoma (8 papers, 2013 to 2025). "Similarly, the PDIA6 expression level was associated with the presence of lymph node metastasis and hormone receptor status in breast cancer." (PMID 33761940, 2021). "For example, PDIA1 and PDIA6 are highly expressed in breast cancer cells (MDA-MB-231, MDA-MB-468, and T47D), whereas PDIA4 (ERp72) expression is high in those two TNBC cells but moderate in T47D cells, indicating a complex transcriptional regulation mechanism." (PMID 35159012, 2022). "More specifically, out of 21 members, PDIA1, PDIA3, PDIA4, and PDIA6 are identified to exhibit an increased mRNA level in breast cancer, according to the Gene Expression Atlas dataset." (PMID 35159012, 2022). "Five of these antigens (VPS35, ARPC2, SERBP1, KRT8, and PDIA6) were selected because they inhibited human breast cancer survival across two aggressive breast cancer subtype cell lines (HER2 positive and triple negative)." (PMID 33976232, 2021). "Four of the antigens (VPS35, SERBP1, KRT8, and PDIA6) decreased growth of the tumors in both mouse mammary tumor models." (PMID 33976232, 2021). "Moreover, the analysis of breast cancer subtypes showed that TNBC tumors express the highest level of PDIA6 and PDIA4 proteins among all the subtypes examined." (PMID 37705743, 2023). "Another proteome analysis indicates that PDIA3 and PDIA6 show higher expression levels in invasive ductal carcinomas than in lobular carcinomas, and the high expression of PDIA3 and PDIA6 genes correlates with the aggressiveness of primary ductal breast cancer." (PMID 35159012, 2022). "It remains to be established in further studies whether, apart from PDIA1, other PDIs including PDIA3, PDIA4 and PDIA6 displaying relative high expression in breast cancer cells and endothelium are also involved in regulating cancer cell interaction." (PMID 33023153, 2020). "Both PDIA6 and PDIA4 protein levels were notably upregulated in primary breast cancers, compared to normal adjacent breast tissues." (PMID 37705743, 2023). "Consistent with the findings, the mRNA levels of PDIA1, PDIA3, PDIA4, and PDIA6 are typically overexpressed in HER2-enriched and Basal-like breast cancer subtypes as evidenced by gene expression data attained from the Gene Expression Atlas datasets." (PMID 35159012, 2022). "We further found that the expression levels of PDIA6 and PDIA4 were higher in breast cancer tissues compared to normal breast tissues, with the highest level observed in the TNBC subtype, suggesting that PDIA6 and PDIA4 could serve as prognostic markers and therapeutic targets for TNBC." (PMID 37705743, 2023).
bladder cancer (7 papers, 2019 to 2025). "Recent researches indicated that PDIA6 was upregulated in human cancers such as liver cancer and bladder cancer." (PMID 38029391, 2023). "In bladder cancer, we screened seven hub genes (ACLY, CNP, NKIRAS2, P3H4, PDIA6, VPS25 and XPO1) associated with survival." (PMID 37601252, 2023). "Silencing of the PDIA6 gene significantly inhibited bladder cancer cell proliferation, invasion, and in vivo tumor formation and metastasis." (PMID 33761940, 2021). "Recently, researches have demonstrated that PDIA6 is overexpressed in several kinds of human cancers and serves as an oncogene, such as lung cancer, bladder cancer, and hepatocellular carcinoma." (PMID 33761940, 2021). "The Wnt/β-catenin signaling pathway can be activated by PDIA6, and the overexpressed PDIA6 promotes proliferation and growth of bladder cancer cells and HeLa cells." (PMID 31467922, 2019). "Moreover, knocking down PDIA6 expression can reduce the proliferation and invasion of bladder cancer cells." (PMID 38029391, 2023). "PDIA6 expression pattern in OSCC was consistent with NSCLC, bladder cancer, ovarian cancer, and hepatocellular carcinoma." (PMID 33761940, 2021).
pancreatic cancer (7 papers, 2017 to 2026). "For instance, PDIA6 promotes immune escape in pancreatic cancer through the deubiquitinitation of PD-L1." (PMID 37686682, 2023). "PDIA6 has been shown to promote pancreatic cancer progression and immune evasion through β-catenin and PD-L1 deubiquitination." (PMID 36291587, 2022). "The interplay between GSTP1, DDAH1 and PDIA6 highlights the complexity of redox regulation in pancreatic cancer and suggests that targeting GSTP1 may offer a new therapeutic approach for PDAC." (PMID 40719618, 2025). "Protein disulfide isomerase family A member 6 (PDIA6) interacts with DUB COPS5 and contributes to pancreatic cancer progression." (PMID 35884607, 2022). "Western blot analysis revealed that PDI expression is low in pancreatic cancer cells compared to other cell lines; MIA PaCa-2 cells possessed the lowest expression of PDI, ERp57, PDIA6, and AGR3." (PMID 29262583, 2017). "By uncovering complex interactions between different omics layers and identifying connections between key molecular players such as PDIA6 and DDAH1, multiomics analysis holds great promise for advancing precision medicine and improving outcomes in pancreatic cancer patients." (PMID 40719618, 2025).
glioma (6 papers, 2020 to 2022). A benign or malignant brain and spinal cord tumor that arises from glial cells (astrocytes, oligodendrocytes, ependymal cells). "The oncogenic cytokines derived from BM-MSCs may upregulate the expression of PDIA6, which reacts with the integrins in microenvironmental niches to facilitate cell-extracellular matrix adhesion, such as integrin α2β1, to promote the invasion and migration of glioma." (PMID 33628783, 2021).
lung adenocarcinoma (4 papers, 2017 to 2023). A carcinoma that arises from the lung and is characterized by the presence of malignant glandular epithelial cells. "PDIA6 increased the resistance of lung adenocarcinoma cells to chemotherapeutic drugs through inhibition of apoptosis and autophagy of cancer cells, and inhibition of PDIA6 promoted the sensitivity of gastric cancer cells to cisplatin." (PMID 34781823, 2021). "Protein disulfide isomerase family 6 (PDIA6) was involved in the chemo-resistance of lung adenocarcinoma." (PMID 34781823, 2021). "ERp72 (PDIA4) and ERp5 (PDIA6) mediate resistance to cisplatin-induced cell death in lung adenocarcinoma." (PMID 29262583, 2017). "Knockdown of PDIA6 promoted cell apoptosis of cisplatin-resistant lung adenocarcinoma cells." (PMID 34781823, 2021). "Furthermore, PDIA4 and PDIA6 regulate cisplatin-induced lung adenocarcinoma cell death resistance." (PMID 36291587, 2022).
lung carcinoma (4 papers, 2016 to 2023). "PDIA6 induces apoptosis of lung cancer cells by regulating the MAP4K1/JNK signaling pathway." (PMID 34616670, 2021). "The expression level of PDI was increased in lung cancer, and its members PDIA4 and PDIA6 were up-regulated in response to cisplatin treatment." (PMID 37315289, 2023). "It is worth noting that, among these identified proteins, five proteins (Hsp90, ENO1, ALDOA, PDIA6, HSPA5) were reported as the differential proteins identified in lung cancer tissues as compared to normal lung in our previous work." (PMID 27684953, 2016).
diabetes (3 papers, 2021 to 2024). "PDIA6 has been implicated in β‐cell dysfunction and diabetes, although its precise function in β cells in vivo remains poorly understood." (PMID 38742851, 2024). "One of the PDI members is the PDI-associated 6 (PDIA6) protein, which has been shown to play a vital role in β-cell dysfunction and diabetes." (PMID 34487921, 2021). "Taken together, the phenotype of Pdia6F175S−/− mice points to hallmarks of an early onset diabetic phenotype, signifying the contribution of PDIA6 in the maintenance of β-cell identity and the development of diabetes." (PMID 34487921, 2021). "The evidence from these in vitro studies collectively implicates a role of PDIA6 in β-cell function and development of diabetes, which is further supported by a recent study that reported dysregulation of Pdia6 in a T1DM model." (PMID 34487921, 2021). "qRT‐PCR analysis indicated significant upregulation of PDIA6 and SLC16A1 mRNA levels in individuals with diabetes when compared to healthy volunteers." (PMID 38742851, 2024). "To investigate the significance of PDIA6 and SLC16A1 in diabetes, we examined their expression in blood specimens obtained from 60 patients with T2DOPand 60 healthy controls." (PMID 38742851, 2024).
gastric cancer (3 papers, 2021 to 2023). A primary or metastatic malignant neoplasm involving the stomach. "Knockdown of PDIA6 reduced protein expression of Wnt3a and β-catenin in gastric cancer cells, and activation of Wnt pathway through incubation with lithium chloride attenuated PDIA6 silencing-induced increase in chemosensitivity." (PMID 34781823, 2021). "Furthermore, PDIA6 upregulation enhanced cisplatin resistance in gastric cancer cells." (PMID 36839749, 2023).
lymph node metastasis (3 papers, 2021 to 2023). "In addition, the relationship between clinicopathological features and PDIA6 expression levels in patients with endometrial cancer was shown in Table I, indicating a significant correlation between PDIA6 expression and FIGO stage and lymph node metastasis in patients with endometrial cancer." (PMID 38097564, 2023).
non-small cell lung carcinoma (3 papers, 2020 to 2022). A group of at least three distinct histological types of lung cancer, including non-small cell squamous cell carcinoma, adenocarcinoma, and large cell carcinoma. "The combination of CALR and PDIA3 has also been suggested as a possible prognostic biomarker for non-small-cell lung cancer, with PDIA6 modulating apoptosis and autophagy of non-small-cell lung cancer cells via the MAP4K1/JNK signalling pathway." (PMID 36291587, 2022).
COVID-19 (2 papers, 2021 to 2023). A disease caused by infection with severe acute respiratory syndrome coronavirus 2. "A previous study also found PDIs, particularly P4HB and PDIA6, in COVID-19 platelets." (PMID 37681923, 2023). "Finally, the levels of two different protein disulfide isomerases, P4HB and PDIA6, which support thrombosis, were increased in the platelets of COVID-19 patients." (PMID 34859078, 2021).
endometrial cancer (2 papers, 2023 to 2025). Primary or metastatic malignant neoplasm involving the endometrium (mucous membrane that lines the endometrial cavity). "PDIA6 have been reported to be involved in a variety of cancers, however, the underlying role in endometrial cancer is still unclear." (PMID 38097564, 2023). "In conclusion, this study proved that PDIA6 is upregulated in endometrial cancer tissues and high PDIA6 expression is associated with tumor progression." (PMID 38097564, 2023). "In endometrial cancer, PDIA6 influences malignant behavior through the TGF‐β pathway and its interactions with the TRPM2‐AS/miR‐424‐5p axis." (PMID 40371728, 2025). "The subsequent rescue experiments showed that the inhibitory impacts of TRPM2-AS knockdown on growth and metastasis of endometrial cancer, were attenuated by miR-424-5p downregulation or PDIA6 overexpression both in phenotype and protein molecular level." (PMID 38097564, 2023). "In summary, these findings all together illustrated the carcinogenic effect of PDIA6 in the malignant biological behavior of endometrial cancer." (PMID 38097564, 2023). "Firstly, we verified that PDIA6 was significantly upregulated in endometrial cancer, which was correlated with the progression of endometrial cancer patients." (PMID 38097564, 2023). "We co-transfected TRPM2-AS knockdown and PDIA6 overexpression lentiviruses into endometrial cancer cells." (PMID 38097564, 2023). "The protein expression of PDIA6 was increased in endometrial cancer tissues based on CPTAC database." (PMID 38097564, 2023). "To investigate the molecular mechanism of PDIA6 in endometrial cancer progression in depth, we knocked down PDIA6 in AN3CA cells and performed transcriptome sequencing." (PMID 38097564, 2023). "We demonstrated that PDIA6 promotes endometrial cancer cell proliferation and metastasis through TGF-β signaling pathway for the first time." (PMID 38097564, 2023). "In this study, we indicated that PDIA6 was significantly overexpressed in endometrial cancer tissues and correlated with the ability of endometrial cancer cells to proliferation and metastatic properties, so it was selected for further study." (PMID 38097564, 2023). "To further elucidated the role of PDIA6 in endometrial cancer progression, we generated a subcutaneous xenograft tumor mouse model of endometrial cancer." (PMID 38097564, 2023). "According to TCGA database and GSE17025 dataset, the mRNA expression of PDIA6 in endometrial cancer tissues was higher than that in normal tissues." (PMID 38097564, 2023). "At the same time, qRT-PCR results showed that PDIA6 mRNA were relatively highly expressed in endometrial cancer cell lines (Ishikawa, AN3CA, HEC-1A, RL-95) compared with HESC." (PMID 38097564, 2023). "On the other hand, after transfection of PDIA6 overexpressing lentivirus into endometrial cancer cells, qRT-PCR was used to verify the transfection efficiency." (PMID 38097564, 2023). "Transwell assay and Wound healing assay showed that the metastatic ability of endometrial cancer cells was significantly enhanced after PDIA6 expression was upregulated." (PMID 38097564, 2023). "Then we aimed to investigate the regulatory mechanism of PDIA6 in endometrial cancer cells." (PMID 38097564, 2023). "Moreover, the expression levels of miR-424-5p and PDIA6 in endometrial cancer samples and their relationship were analyzed based on the ENCORI project (r = −0.217, p = 3.83e-07)." (PMID 38097564, 2023). "It is suggested that PDIA6 could be used as one of the indicators to predict the prognosis of patients with endometrial cancer." (PMID 38097564, 2023). "Consistently, qRT-PCR was performed to verify the changes of PDIA6 expression in specimens pathologically diagnosed as endometrial cancer at Qilu Hospital, and the results showed that the mRNA level of PDIA6 in endometrial cancer tissues was frequently upregulated, compared to the normal tissues." (PMID 38097564, 2023).
endometrial cancer (continued). "Therefore, we demonstrated that PDIA6 expression was regulated by TRPM2-AS/miR-424-5p axis in endometrial cancer." (PMID 38097564, 2023). "In this research, we found PDIA6 was overexpressed in endometrial cancer, and PDIA6 could regulate the proliferation and metastatic ability of endometrial cancer cells." (PMID 38097564, 2023). "In this study, we aimed to study the function of PDIA6 in endometrial cancer." (PMID 38097564, 2023). "Transwell assay and Wound healing assay confirmed that knockdown PDIA6 could decrease the ability of migration and invasion in endometrial cancer cells compared with the control group respectively." (PMID 38097564, 2023). "We hypothesized that PDIA6 could promote the growth and metastasis of endometrial cancer cells by regulating TGF-β pathway and being regulated by TRPM2-AS/miR-424-5p axis." (PMID 38097564, 2023). "Furthermore, TRPM2-AS/miR-424-5p axis was verified as the upstream molecule that directly targeted PDIA6 and regulated the biological function of PDIA6 in endometrial cancer." (PMID 38097564, 2023). "Taken together, this study suggested that PDIA6 may be a new candidate target for endometrial cancer therapy." (PMID 38097564, 2023). "Furthermore, we identified PDIA6 significantly altered the ability of endometrial cancer cells to proliferate and metastasize." (PMID 38097564, 2023). "In addition, our result illustrated the oncogene effects of PDIA6 in promoting malignant biological behavior of endometrial cancer cells by regulating TGF-β pathway and being modulated by TRPM2-AS/miR-424-5p axis for the first time." (PMID 38097564, 2023). "IHC results were carried to show that PDIA6 was highly expressed in endometrial cancer." (PMID 38097564, 2023). "Therefore, we indicated that PDIA6 may be an oncogene and play an essential role in promoting endometrial cancer progression." (PMID 38097564, 2023). "Since the effects of PDIA6 in endometrial cancer has not been reported, we conducted a series of experiments to study the function of PDIA6 in endometrial cancer cells." (PMID 38097564, 2023). "The results showed that only miR-424-5p mimics decreased PDIA6 expression, miR-195-5p and miR-497-5p could not alter PDIA6 expression in endometrial cancer cells." (PMID 38097564, 2023). "However, the effects of PDIA6 in endometrial cancer has not yet been fully established." (PMID 38097564, 2023).